ENSG00000275908
Gene: Small nuclear RNA gene on chromosome 16 (20,823,443 to 20,823,537, forward strand). Ensembl gene ENSG00000275908.
Homologues: Paralogues in human: RNU4ATAC16P (80% identical), RNU4ATAC2P (77% identical), RNU4ATAC18P (76% identical), RNU4ATAC11P (68% identical).